USP44 (ubiquitin specific peptidase 44)
Diseases named in the same sentence as USP44 in open-access papers (continued):
Sharing a sentence is not in itself a finding about the gene and the disease.
thyroid cancer (1 paper, 2024). "In summary, our findings indicate that USP44 is frequently downregulated due to promoter methylation in thyroid cancer and is strongly associated with a poor patient prognosis." (PMID 39430240, 2024). "Nonetheless, the specific functions and underlying mechanisms of USP44 in thyroid cancer remain to be comprehensively elucidated." (PMID 39430240, 2024). "To explore the mechanism underlying the tumor-suppressing function of USP44 in thyroid cancer, we first identified USP44-interacted proteins by liquid chromatography tandem mass spectrometry (LC-MS/MS) combined with co-IP." (PMID 39430240, 2024). "However, the underlying roles of USP44 in thyroid cancer remain elusive." (PMID 39430240, 2024). "To further determine whether USP44 deficiency exacerbates the progression of thyroid cancer, we generated thyroid-specific Usp44 knockout mouse model of BrafV600E-induced thyroid cancer by crossing LSL-BrafV600E, LSL-Usp44 and thyroid peroxidase (Tpo)-Cre mice." (PMID 39430240, 2024). "Collectively, our data indicate that promoter methylation of USP44 is one of the major mechanisms of its downregulation in thyroid cancer." (PMID 39430240, 2024). "In this study, we find that USP44 is downregulated by promoter hypermethylation in thyroid cancer and its downregulation is strongly correlated with unfavorable patient survival outcomes." (PMID 39430240, 2024). "Subsequent in vitro and in vivo functional studies revealed that USP44 substantially suppressed the proliferation of thyroid cancer cells by impeding the G1/S transition in cell cycle." (PMID 39430240, 2024). "In this study, we provided compelling evidence to support USP44 as a tumor suppressor gene in thyroid cancer." (PMID 39430240, 2024). "Our findings, taken together, indicate that USP44 is frequently repressed in thyroid cancer due to promoter hypermethylation and functions as a tumor suppressor by stabilizing p21 via deubiquitination." (PMID 39430240, 2024). "To determine the potential role of USP44 in thyroid cancer, we performed a series of in vitro functional experiments in thyroid cancer cells." (PMID 39430240, 2024). "Specifically, USP44 inhibited the proliferation and colony formation abilities of thyroid cancer cells, reduced tumor growth in nude mice and transgenic mice and induced G1/S arrest." (PMID 39430240, 2024). "Altogether, these findings strongly indicate that USP44 is essential for cell cycle regulation and acts as a tumor suppressor in thyroid cancer cells." (PMID 39430240, 2024). "Collectively, these data indicate that USP44 mediates G1/S transition and suppresses the growth of thyroid cancer cells by regulating p21expression." (PMID 39430240, 2024). "In this study, we observed that USP44 was frequently downregulated by promoter hypermethylation in thyroid cancers and found that its decreased expression was closely associated with poor patient survival." (PMID 39430240, 2024). "The results showed that ectopic expression of USP44 evidently inhibited the proliferation and colony formation ability of thyroid cancer cells." (PMID 39430240, 2024). "Indeed, our findings showed that USP44 overexpression significantly inhibited the G1/S transition and cell proliferation of thyroid cancer cells, and vice versa." (PMID 39430240, 2024). "Functional studies demonstrate that USP44 acts as a tumor suppressor in thyroid cancer cells." (PMID 39430240, 2024).
thyroid cancer (continued). "We next conducted MSP assay to detect USP44 methylation in a panel of thyroid cancer cell lines and immortalized thyroid follicular cell line HTori3, and found different levels of USP44 methylation in each of these thyroid cancer cell lines compared to HTori3 cell line." (PMID 39430240, 2024). "However, USP44 is downregulated or even inactivated by promoter hypermethylation in thyroid cancer, thus losing its tumor-suppressing function." (PMID 39430240, 2024). "In this study, we found that USP44 was frequently downregulated by promoter methylation in thyroid cancers, as confirmed by MSP assays and demethylation treatment in a panel of thyroid cancer cell lines." (PMID 39430240, 2024).
thyroid gland disorder (1 paper, 2024). A disease involving the thyroid gland. "USP44 expression was negatively associated with T stage (P < 0.001), N stage (P = 0.002), pathologic stage (P < 0.001), age (P = 0.027), histological type (P < 0.001), extrathyroidal extension (P < 0.001) and thyroid gland disorder history (P = 0.008)." (PMID 39430240, 2024). "Moreover, we also observed that USP44 expression was negatively associated with BRAFV600E mutation, tumor stage, histological type, extrathyroidal extension and thyroid gland disorder history, and reduced USP44 expression was positively correlated with poor clinical outcomes of patients." (PMID 39430240, 2024).
thyroid tumor (1 paper, 2024). A benign or malignant neoplasm affecting the thyroid gland. "We also analyzed histological pathology of thyroid tumors at sixth week by hematoxylin and eosin (H&E), and found that Usp44 knockout combined with BrafV600E accelerated the formation of papillary thyroid architecture compared to BrafV600E alone." (PMID 39430240, 2024). "Follow-up ultrasound scan showed that thyroid tumors in homozygous Usp44 knockout mice (Braf m/+; Usp44-/-) grew more rapidly than that in Usp44 wild-type mice (Braf m/+; Usp44+/+) at tenth week, consistent with the gross appearance following dissection." (PMID 39430240, 2024).
cancer (34 papers, 2009 to 2025). A tumor composed of atypical neoplastic, often pleomorphic cells that invade other tissues. "To further evaluate its role of in cancer, we cross-referenced the USP44 proximity proteome data with the Cancer Gene Census curated by the Catalogue of Somatic Mutations in Cancer (COSMIC|Catalogue of Somatic Mutations in Cancer (sanger.ac.uk))." (PMID 39767807, 2024). "Our data suggest that USP44 forms complexes with several known cancer genes implicated in several different cancer types." (PMID 39767807, 2024). "Therefore, loss of USP44 expression by methylation is expected to increase genomic instability in cancer." (PMID 34572834, 2021). "DBH‐AS1 is upregulated by METTL3‐mediated m6A modification, and overexpression of DBH‐AS1 sponges miR‐3163 and upregulates the expression of USP44, a target gene of miR‐3163, thereby reducing gemcitabine resistance and suppressing cancer growth." (PMID 40448344, 2025). "We have a longstanding interest in the role of deubiquitinating enzymes in cancer and have shown that the enzyme USP44 has both tumor-suppressive and oncogenic roles." (PMID 39767807, 2024). "Subsequently, we and others have found USP44 to contribute to the pathophysiology of several cancers, with roles as an oncogene and tumor suppressor depending on the cellular context of its deregulation." (PMID 39767807, 2024). "Ubiquitin-specific peptidase 44 (USP44) belongs to the ubiquitin-specific protease family and is pivotal in the development and progression of tumors across various human cancers." (PMID 39430240, 2024). "When compared with those proteins isolated from cells expressing BioID alone, we identified 146 proteins in the proximity of USP44, including many known cancer-related proteins." (PMID 39767807, 2024). "We therefore performed a proximity biotinylation study that identified products of several known cancer genes that are associated with USP44, including a novel interaction between BRCA2 and USP44." (PMID 39767807, 2024). "Knockdown experiments also suggested that USP44 promotes tumorigenic and cancer stem cell characteristics in PC3 and DU145 cells." (PMID 39095452, 2024). "Previous reports have demonstrated that USP44 plays diverse roles in the initiation and development of cancer." (PMID 38097536, 2023). "Recent studies have shown that ubiquitin-specific protease 44 (USP44) is a cancer suppressor gene or oncogene, depending on the type of tumor." (PMID 35836256, 2022). "Our previous studies indicated that TRIM28‐dependent ubiquitination and USP44‐dependent deubiquitination of FBP1 regulated its stability in cancer cells." (PMID 34854226, 2022). "Experimental studies have found that the expression level of USP44 is significantly reduced in CRC and enhances the apoptosis of CRC cells, indicating that USP44 is a cancer suppressor of CRC." (PMID 35836256, 2022). "We previously demonstrated that the deubiquitinase USP44 is a potent tumor suppressor in mice and that reduced USP44 levels are also seen in human cancers." (PMID 33937266, 2021). "Few studies have attempted so far to elucidate the clinical significance of USP44 promoter methylation in cancer patients." (PMID 34572834, 2021). "The same group reported that USP44 overexpression significantly suppressed cancer cell proliferation, migration, and invasion and induced apoptosis." (PMID 34572834, 2021). "Our study found that USP44 inhibited proliferation while enhancing apoptosis in CRC cells, indicating that USP44 is a cancer suppressor in CRC." (PMID 32285989, 2020). "We next set out to test the notion that USP44 expression by Tregs contributes to their pathological suppression of anti‐tumor immunity in cancer models." (PMID 32644293, 2020). "Recent studies have revealed that ubiquitin‐specific protease 44 (USP44) is a cancer suppressor or oncogene depending on the type of neoplasm." (PMID 32285989, 2020).
cancer (continued). "Data obtained from the Cancer Genome Atlas Data Portal and Gene Expression Omnibus database were analyzed to uncover the clinical relevance of USP44 expression and tumor development." (PMID 32164618, 2020). "Our findings suggestive of a pro‐tumor role for Treg‐specific USP44 are particularly interesting in light of past studies of USP44 in the cancer setting." (PMID 32644293, 2020). "USP44 is a member of a family of deubiquitinating enzymes and has an important role in human cancers." (PMID 32164618, 2020). "Recent studies have revealed that USP44 plays opposing roles in different cancers, either suppressing or promoting cancer development." (PMID 32285989, 2020). "On the other hand, among the 207 cancer cases, 90 cases (43.5%) showed USP44‐positive expression in over 40% of nuclei." (PMID 28544703, 2017). "Although further experiments will be required to determine the functions of USP44 and its role within cancer, our findings will be helpful for clinical molecular classification." (PMID 28544703, 2017). "For example, USP44 gene expression was significantly negatively correlated with DNA methylation across all cancer types (all r < -0.2, p < 0.05)." (PMID 28060724, 2017). "The mean values were 14.6% positive USP44 expression in normal mucosa and 39.6% in cancer (P < 0.0001)." (PMID 28544703, 2017). "USP44 plays a role in cancer through its dysregulation of the DNA damage response mediated by the E3 ligase RNF168 on histone H2A." (PMID 25605410, 2015). "Comparing cancer to normal tissues, eight cancer groups have significant alteration in the level of USP44." (PMID 21853124, 2011). "While some binding partners and substrates are known for USP44, the identification of other interactions may improve our understanding of its role in cancer." (PMID 39767807, 2024). "A copy number meta-analysis of 12 human cancer types showed that USP44 is a novel tumor suppressor." (PMID 37204480, 2023). "Moreover, USP44 has been reported to regulate various functions, such as metastasis and DNA damage response in other cancer types." (PMID 37204480, 2023). "Recently, several studies revealed the characteristics of USP44 in cancers." (PMID 36483601, 2022). "USP44 also regulated apoptosis of cancer cells in a cell-dependent way." (PMID 36483601, 2022). "Besides, USP44 and WDR5 are also associated with the metastasis of cancer, such as the migration and invasion capability of cancer cells and vasculogenic mimicry 12, 13, 27, 36-38." (PMID 36483601, 2022). "Furthermore, we detected 143 variants in 66 cancer-associated genes, including BMP5, with the highest predicted deleteriousness score of 22.7, MET and USP44." (PMID 34069790, 2021). "In colorectal neoplasia an interaction between USP44 promoter methylation and cancer was shown." (PMID 34572834, 2021). "USP44 is a cancer suppressor in CRC and a potential target for CRC therapy." (PMID 32285989, 2020). "USP44 showed low expression in ccRCC cancer tissues compared with that in normal tissue." (PMID 32164618, 2020). "The abnormal expression of USP44 has been found in many cancers." (PMID 32285989, 2020). "Importantly, USP44 presents a potential target for immunotherapeutic intervention for dysregulated immune responses such as those seen in autoimmune diseases and cancer." (PMID 32644293, 2020). "We speculate that the unknown functions of USP44 and DNA aneuploidy may have synergistic progressive effects on cancer invasion and metastasis." (PMID 28544703, 2017). "Notably, USP44 was also found frequently down-regulated in human bronchial adenocarcinomas and patients with low USP44 expression had significantly shorter overall survival, underscoring a tumor suppressive function in human cancer." (PMID 26442100, 2015). "The proposed antagonistic relationship between this enzyme and USP44 raise the possibility that alterations in the ubiquitination status of Cdc20-APC/C or its substrates may be a recurring theme in a number of cancers." (PMID 21853124, 2011).
cancer (continued). "Therefore, USP44 is a cancer suppressor in CRC and a potential target for CRC therapy." (PMID 32285989, 2020). "However, there is still controversy about the precise role that USP44 plays in cancer." (PMID 28938551, 2017). "Therefore, a balance between UbcH10 and Usp44 could determine the appropriate timing of sister chromatid separation and further explain the significance of UbcH10 in cancer." (PMID 19302711, 2009). "Ubiquitin-specific protease 44 (USP44), a member of the cysteine protease family, has been reported to play a role in many cancer types." (PMID 37204480, 2023). "For instance, NOVA1, NRXN1, TMEM132C, USP44, VIPR2, and ZSCAN23 were consistently downregulated in nine cancers." (PMID 28060724, 2017). "Here, I will focus on the emerging roles of the H2A DUBs USP3, USP16, USP44, BAP1, and MYSM1 in HSC maintenance and cancer." (PMID 26442100, 2015). "While multiple potential mechanisms have been identified to mediate the roles of USP44 in cancer, to our knowledge there has been no unbiased examination of the USP44 interactome to help uncover oncogenic or tumor-suppressive mechanisms." (PMID 39767807, 2024). "According to the results presented in this study, USP44 regulates enhancer of zeste homolog 2 (EZH2), a histone H3 lysine 27 methyltransferase, which is involved in the development and progression of various cancers." (PMID 34572834, 2021). "Our present findings suggest that targeting factors such as USP44 and USP7 that promote FOXP3 expression at the protein level is a strategy that offers exciting possibilities for the fine‐tuning of immune responses in cancer." (PMID 32644293, 2020). "Tregs genetically lacking USP44 are less effective than their wild‐type counterparts, both in vitro and in multiple in vivo models of inflammatory disease and cancer." (PMID 32644293, 2020). "Here, we found that the USP44 expression level was markedly decreased in CRC, and USP44 overexpression inhibited proliferation while enhancing apoptosis in CRC cells, suggesting that USP44 is a cancer suppressor in CRC." (PMID 32285989, 2020). "DUBs are critical key players in diverse processes such as (i) spermatogenesis (e.g. USP2, USP8, USP9y, USP14, USP26, Uchl-1, Uchl-3 and CYLD), (ii) cancer biology (e.g. USP7, USP10 and USP11), and (iii) stemness and differentiation (e.g. USP7, USP9x, USP22, USP44 and Psmd14)." (PMID 28659380, 2017). "Notably, the potential role of USP44 as a regulator of the anti‐tumor immune response was not explored in any of these studies, and, indeed, the ability of this and other DUBs to control FOXP3 expression and Treg function in cancer has yet to be explored in detail." (PMID 32644293, 2020).